INS (insulin)
Diseases named in the same sentence as INS in open-access papers (continued):
Sharing a sentence is not in itself a finding about the gene and the disease.
type 1 diabetes (continued). "The OhioT1DM dataset, a valuable resource, comprises dietary information from 12 patients with type 1 diabetes, insulin dosage details, and blood glucose values from 12 type 1 diabetic patients, encompassing 7 males and 5 females." (PMID 41452855, 2025). "Despite advances in treatment, most people with type 1 diabetes will depend on insulin for their entire lives." (PMID 40232951, 2025). "The literature has shown that aerobic exercise is associated with post-exercise reductions in glycemia in individuals with type 1 diabetes, by improving glucose uptake in skeletal muscle and increasing insulin sensitivity." (PMID 40407447, 2025). "Type 1 diabetes is an autoimmune disease characterized by the gradual depletion of beta cell mass, resulting in insufficient insulin secretion to maintain normal blood glucose levels." (PMID 40831568, 2025). "We found a three- to fourfold higher peripheral insulin concentration in participants with type 1 diabetes than in control participants." (PMID 40210728, 2025). "Insulin plays a vital role in the regulation of lipid metabolism and lipid disorders are commonly diagnosed in individuals with type 1 diabetes." (PMID 40019499, 2025). "Subgroup analyses showed these trends were more pronounced among individuals with type 1 diabetes, those previously treated with insulin, and at longer follow‐up durations." (PMID 40509887, 2025). "The program demonstrated improvements in time in range and glycemic variability with sotagliflozin in combination with insulin in adults with type 1 diabetes." (PMID 41551500, 2025). "Autoreactive B cell activity defines the earliest detectable stage (Stage 1) of type 1 diabetes (T1D) but is incompletely understood, particularly for B cells reactive against the key T1D autoantigen, insulin." (PMID 41259806, 2025). "The baseline characteristics of participants with type 1 diabetes randomized to metformin or placebo were similar, except for a lower total daily insulin dose in the metformin group." (PMID 41285865, 2025). "This updated meta‐analysis evaluates the efficacy and safety of metformin as add‐on therapy to insulin in patients with type 1 diabetes." (PMID 40512873, 2025). "The assessment provides a differentiated picture of the evidence base for various insulin treatment alternatives that people with type 1 diabetes and clinicians can choose from." (PMID 40270713, 2025). "Research indicates a strong correlation between Type 1 diabetes and PCOS, with studies suggesting that at least 25% of women with Type 1 diabetes, particularly those using exogenous insulin, are likely to develop PCOS." (PMID 40723460, 2025). "The delayed diagnosis of type 1 diabetes increases the risk for DKA and is associated with reduced residual insulin secretory capacity, and therefore, a shorter and less pronounced remission period." (PMID 40406224, 2025). "Type 1 diabetes is a relatively rare autoimmune disease that occurs when the immune system attacks the insulin‐producing β‐cells of the pancreas." (PMID 41280745, 2025). "We analyzed pancreatic islet cells from donors with type 1 diabetes to define pathways and mechanisms responsible for altered insulin and glucagon in this disease." (PMID 41026524, 2025). "Studies showed that sotagliflozin added to optimized insulin therapy led to lower rates of clinically relevant hypoglycemic events at 52 weeks in adults with type 1 diabetes." (PMID 41551500, 2025). "Managing type 1 diabetes (T1D) requires maintaining target blood glucose levels through precise diet and insulin dosing." (PMID 41264796, 2025). "Type 1 diabetes (T1D) is a complex autoimmune disorder characterized by the selective destruction of insulin-producing pancreatic β-cells." (PMID 41373764, 2025). "In general, 35-70% of type 1 diabetes patients experience a period where they temporarily reduce the amount of insulin, called the “honeymoon period”." (PMID 40135013, 2025).
type 1 diabetes (continued). "Thus, the effectiveness of PP infusion in decreasing insulin requirements could be correlated with the degree of PP deficiency present in these patients, suggesting a possible therapeutic role of PP in type 1 diabetes mellitus (T1DM), as well as T3cDM patients." (PMID 39857716, 2025). "Type 1 diabetes mellitus (T1DM) is an autoimmune disease characterized by the immune-mediated destruction of insulin-producing pancreatic beta cells, resulting in hyperglycemia and lifelong insulin dependence." (PMID 40525066, 2025). "Type 1 diabetes is a chronic, autoimmune disease characterized by the destruction of insulin-producing β-cells in the pancreas." (PMID 40263317, 2025). "In the last few years, there have been many technological advances in glucose monitoring and insulin delivery, which have resulted in new opportunities for the treatment of type 1 diabetes." (PMID 39387915, 2025). "This systematic review and meta-analysis investigates if, compared with standard care, automated insulin delivery systems used in an outpatient setting improve measures of glucose management and quality of life in children and adolescents with type 1 diabetes." (PMID 40920375, 2025). "Numerous studies have shown that miRNAs have a part in the pathophysiology of type 1 diabetes, mainly by interfering with the activity, secretion, and synthesis of insulin by pancreatic β-cells." (PMID 41361288, 2025). "This highlights the need for careful insulin management in children and adolescents with type 1 diabetes engaging in VPA." (PMID 38954647, 2025). "Type 1 diabetes (T1D) is an autoimmune disease characterised by the destruction of insulin‐producing pancreatic β‐cells." (PMID 40968543, 2025). "Type 1 diabetes is an autoimmune disease where insulin-producing beta cells of the pancreas are destroyed by infiltrating immune cells, leading to insulin deficiency." (PMID 39477880, 2025). "Type 1 diabetes (T1D) is an incurable autoimmune disease where the body attacks insulin-producing beta (β) cells." (PMID 40869787, 2025). "These cells play a crucial role in the pathogenesis of type 1 diabetes by attacking the pancreatic beta cells, leading to insufficient insulin secretion." (PMID 41174657, 2025). "Type 1 Diabetes Mellitus (T1D) is a chronic disease which is characterised by the autoimmune destruction of the insulin secreting β cells in the pancreatic islets by T lymphocytes (CTLs), leading to insulin deficiency." (PMID 40093006, 2025). "Boiroux and Jørgensen evaluated the performance of a nonlinear model predictive control algorithm for closed-loop insulin delivery in type 1 diabetes (T1D) management, with simulations demonstrating its safety and efficacy in optimizing insulin administration." (PMID 40465596, 2025). "Type 1 diabetes (T1D) is a chronic autoimmune disorder characterized by the destruction of insulin-producing pancreatic β-cells due to an attack by autoreactive T cells." (PMID 41012130, 2025). "In a study with youth with type 1 diabetes, incentives had a positive impact on glucose monitoring frequency and adherence to the prescribed insulin regimen." (PMID 40810443, 2025). "Our future studies will clarify the dynamic relationship between iatrogenic hyperinsulinemia, insulin sensitivity, and endothelial function in type 1 diabetes." (PMID 40045281, 2025). "Type 1 diabetes (T1D) is characterized by the autoimmune destruction of most insulin-producing β cells, along with dysregulated glucagon secretion from pancreatic α cells." (PMID 41026524, 2025). "Type 1 diabetes is characterized by the destruction of pancreatic β cells, requiring lifelong insulin replacement therapy." (PMID 41022835, 2025). "In Type 1 diabetes (T1D), inadequate insulin secretion results primarily from autoimmune-mediated damage and death of insulin-secreting cells." (PMID 40260393, 2025). "Type 1 diabetes (T1D) is characterized by the autoimmune destruction of insulin-producing β-cells in the pancreas." (PMID 41567805, 2025).
type 1 diabetes (continued). "Type 1 diabetes mellitus (T1DM) is a chronic autoimmune condition characterized by the immune-mediated destruction of insulin-producing pancreatic β-cells, leading to absolute insulin deficiency." (PMID 40647702, 2025). "Type 1 diabetes is difficult to control: patients need multiple insulin injections per day with considering insulin to carb ratio, carb counting and insulin sensitivity factor." (PMID 41026724, 2025). "In a proof-of-concept study, subcutaneously implanted alginate-microencapsulated cells stably expressing an EMPOWER-controlled insulin expression system normalized blood-glucose levels in a mouse model of type 1 diabetes in response to a weak magnetic field." (PMID 40325210, 2025). "Type 1 diabetes (T1D) results from autoimmune-mediated destruction of insulin-producing β cells in the pancreatic islet." (PMID 40463221, 2025). "Type 1 diabetes is a lifelong disease requiring intensive insulin treatment and daily monitoring of blood glucose levels." (PMID 39387915, 2025). "Type 1 diabetes is a chronic disease that is characterised by the autoimmune destruction of insulin-producing pancreatic beta cells." (PMID 39694913, 2025). "For patients with type 1 diabetes and many with advanced type 2 diabetes, insulin therapy remains the cornerstone of management." (PMID 41471093, 2025). "Insulin pumps, or continuous subcutaneous insulin infusion, are an important therapeutic option for people with type 1 diabetes." (PMID 40390300, 2025). "Children with the onset of type 1 diabetes during the COVID-19 pandemic had a significantly higher daily insulin requirement after initiation of therapy." (PMID 40406224, 2025). "Another large prospective study, primarily in adolescents with type 1 diabetes, also demonstrated lower rates of peripheral nerve abnormalities and retinopathy in those on insulin pump therapy." (PMID 40390300, 2025). "We conducted a systematic review to compare the efficacy and safety of glucagon-like peptide 1 receptor agonists (GLP-1 RAs) versus placebo in addition to insulin treatment in patients with type 1 diabetes (T1D)." (PMID 40760325, 2025). "In this open‐label, randomised crossover trial, 18 adults with type 1 diabetes using insulin pump therapy [12 females, age 39.1 (14.2) yrs., HbA1c 57.9 (8.7) mmol/mol] completed two 8‐h inpatient sessions (09:00 to 17:00 h)." (PMID 40815068, 2025). "The standard treatment for Type 1 Diabetes Mellitusstill involves daily parenteral insulin administration, which presentsseveral challenges including patient discomfort, reduced adherence,and the potential for peripheral hyperinsulinemia." (PMID 40488088, 2025). "Type 1 diabetes (T1D) is an autoimmune disease that affects an estimated 30 million people worldwide and results in a lifelong dependency of exogenous insulin treatments." (PMID 40149868, 2025). "In conclusion, DPP-4 inhibitors appear to be safe as adjunctive therapy to insulin in patients with type 1 diabetes." (PMID 41026724, 2025). "Type 1 diabetes (T1D) is characterized by the immune-mediated destruction of insulin-producing β-cells in pancreatic islets." (PMID 41141358, 2025). "The DEPS‐R was developed for use among individuals with type 1 diabetes; thus, six of the 16 items are specific to intensified insulin therapy." (PMID 40440439, 2025). "In populations with a higher risk for insulin purging behaviour, i.e. young women with type 1 diabetes, we highly recommend using the DEPS‐R as a valid instrument for disordered eating, including insulin‐specific compensatory behaviours." (PMID 40440439, 2025). "Further compelling evidence was obtained in a recent clinical trial in which 6 months of treatment with antiviral drugs starting near the diagnosis of type 1 diabetes resulted in preservation of insulin secretion when compared with placebo." (PMID 40090994, 2025). "For patients with type 1 diabetes, the predominant precipitant was insulin omission or under-dosing." (PMID 40940823, 2025).
type 1 diabetes (continued). "Using data from the Italian Behavioral Risk Factor Surveillance System (PASSI) collected between 2011 and 2018 and in 2023, we analyzed key outcomes in adults aged 18–50 who were diagnosed with type 1 diabetes before age 18 and were on insulin therapy." (PMID 41036118, 2025). "T1D, often referred to as juvenile diabetes, is an autoimmune condition where the body’s immune system destroys insulin-producing pancreatic β-cells." (PMID 41149292, 2025). "Type 1 diabetes (T1D), which results from autoimmune destruction of the pancreatic β-cells responsible for insulin production, is a condition that has a complex relationship with periodontal disease." (PMID 40283738, 2025). "Type 1 diabetes mellitus (T1DM) is a severe autoimmune condition characterised by T cell-mediated destruction of insulin-producing β-cells, leading to hyperglycaemia and ketoacidosis if left untreated." (PMID 40755902, 2025). "This research is related to a previous study by the same authors titled Effect of a Dietary Intervention on Insulin Requirements and Glycemic Control in type 1 Diabetes: A 12-Week Randomized Clinical Trial." (PMID 40474900, 2025). "In type 1 diabetes (T1D), insulin-producing β-cells are killed by islet-infiltrating immune cells in a process called ‘insulitis’." (PMID 40232951, 2025). "Type 1 diabetes (T1D) is a chronic autoimmune disorder characterized by immune-mediated destruction of pancreatic beta cells, resulting in impaired insulin secretion and persistent hyperglycemia." (PMID 40963150, 2025). "Insulin is an essential medication for regulating blood glucose levels, particularly in the management of individuals with type 1 diabetes." (PMID 40471961, 2025). "In the DCCT/EDIC study, patients with type 1 diabetes who received intensive insulin therapy had significantly lower incidences of CAN after long-term follow-up compared to those on conventional therapy." (PMID 40564795, 2025). "Type 1 diabetes is an immune-mediated disease that results in a lifelong need for exogenous insulin and a high burden of disease for those affected and the society." (PMID 40768045, 2025). "For example, type 1 diabetes (T1D) is characterized by the destruction of pancreatic β-cells, which are responsible for insulin secretion." (PMID 41373952, 2025). "For people with type 1 diabetes, insulin treatment is essential and must be given by injection under the skin." (PMID 40520684, 2025). "A person with type 1 diabetes requires insulin therapy and must frequently adjust their dosage to meet their glycaemic goals." (PMID 40574088, 2025). "In Colombia, web-based video conferencing was used to train patients with type 1 diabetes who were switching from regular insulin pumps to a hybrid closed-loop system." (PMID 40341010, 2025). "Type 1 diabetes (T1D) is characterised by the autoimmune destruction of pancreatic insulin-producing beta (β) cells and lifelong dependency on exogenous insulin for survival." (PMID 40718205, 2025). "Type 1 diabetes is an autoimmune condition that elicits the destruction of pancreatic beta cells, resulting in a deficit of insulin production." (PMID 38954647, 2025). "Type 1 diabetes (T1D) is an autoimmune disease marked by the destruction of insulin-producing pancreatic beta cells, necessitating lifelong dependence on exogenous insulin." (PMID 40022528, 2025). "In contrast to traditional subcutaneous insulin, inhaled insulin produced quick and long-lasting patient satisfaction as well as a favourable effect on psychological health in individuals with type 1 diabetes." (PMID 40574088, 2025). "Currently, these insulin administration systems represent the pinnacle of insulin delivery technology available for type 1 diabetes management, significantly improving glucose control and lowering hypoglycemia risk." (PMID 40547532, 2025).
type 1 diabetes (continued). "In type 1 diabetes, insulin sensitivity positively correlates with MAGE, while impaired epinephrine response during hypoglycemia significantly increases fluctuation risk." (PMID 41426511, 2025). "In type 1 diabetes, adiponectin plays a role in regulating insulin sensitivity and inflammation, both of which are important for managing the disease." (PMID 40277935, 2025). "This is alarming, as people living with type 1 diabetes depend on a complex regimen of lifelong exogenous insulin therapy, and disease management is constant and difficult, with a high psychological and sociological impact on quality of life." (PMID 41226824, 2025). "Gene therapy for type 1 diabetes (T1D) has predominantly aimed at restoring insulin production by islet cells or their surrogates, or preventing the destruction of β cells." (PMID 39858654, 2025). "Effective management of postprandial glycemic excursions in type 1 diabetes requires accurate prediction of adverse events and personalized insulin adjustments informed by interpretable models." (PMID 40956852, 2025). "In a type 1 diabetes model, impaired insulin signaling promoted cardiac oxidative stress by activating FOXO1 and the expression of PPARα in cardiomyocytes." (PMID 40313619, 2025). "Initially, the FDA declined approval for its use in combination with insulin for type 1 diabetes (T1D)." (PMID 41012462, 2025). "The inTandem1 and inTandem2 trials randomized adults with type 1 diabetes on optimized insulin to sotagliflozin 200 mg, 400 mg, or placebo." (PMID 41551500, 2025). "We aimed to evaluate real‐world glycaemic outcomes of a tubeless hybrid closed‐loop (HCL) insulin delivery system in type 1 diabetes (T1D), exploring the influence of ethnicity and socioeconomic status from a publicly funded system with universal access." (PMID 40631447, 2025). "Hybrid closed-loop (HCL) insulin therapy, combining automated insulin dosing with user-initiated meal bolusing, is becoming the standard of care for people with type 1 diabetes in many countries." (PMID 39560745, 2025). "Type 1 diabetes (T1D), a chronic autoimmune disease, results from lymphocyte-mediated destruction of islet-specific β-cells leading to insulin shortage and hyperglycemia." (PMID 40247205, 2025). "It is well-known that the pathogenesis of type 1 diabetes leads to the serious destruction of pancreatic islets, which are the main sources of insulin production." (PMID 40497986, 2025). "The onset of type-1 diabetes shows an autoimmune inflammatory process destructing pancreatic β-cells and leading to a lifelong necessity of insulin substitution for patients." (PMID 41514592, 2025). "In 1935, Himsworth described the difference between type 1 diabetes (insulin sensitive) and T2DM (insulin insensitive)." (PMID 40565766, 2025). "Her type 1 diabetes control was optimized with HbA1C 6.0% on insulin lispro 3-4 units with each meal and insulin degludec 5 units every night at bedtime." (PMID 41165217, 2025). "In young adults with type 1 diabetes, intensive insulin therapy remains a central component of DKA treatment." (PMID 41149081, 2025). "Type 1 diabetes (T1D) is an autoimmune disease that requires insulin to regulate blood glucose levels and sustain life." (PMID 39910931, 2025). "Type 1 diabetes (T1D) is a severe pathology of the endocrine pancreas, which is related to the autoimmune destruction of insulin-secreting β-cells." (PMID 39860066, 2025). "Type 1 diabetes (T1D) is a chronic, lifelong condition that requires rigid management through daily glucose monitoring and dosing of insulin, either by injections or through a pump." (PMID 40150265, 2025). "Type 1 diabetes (T1D), an autoimmune disease characterized by the body’s inability to produce insulin, affects 5–10% of all diabetes patients." (PMID 40859872, 2025).